TDG (thymine DNA glycosylase)
Description:
DNA glycosylase that plays a key role in active DNA demethylation: specifically recognizes and binds 5-formylcytosine (5fC) and 5-carboxylcytosine (5caC) in the context of CpG sites and mediates their excision through base-excision repair (BER) to install an unmethylated cytosine. Cannot remove 5-hydroxymethylcytosine (5hmC). According to an alternative model, involved in DNA demethylation by mediating DNA glycolase activity toward 5-hydroxymethyluracil (5hmU) produced by deamination of 5hmC. Also involved in DNA repair by acting as a thymine-DNA glycosylase that mediates correction of G/T mispairs to G/C pairs: in the DNA of higher eukaryotes, hydrolytic deamination of 5-methylcytosine to thymine leads to the formation of G/T mismatches. Its role in the repair of canonical base damage is however minor compared to its role in DNA demethylation. It is capable of hydrolyzing the carbon-nitrogen bond between the sugar-phosphate backbone of the DNA and a mispaired thymine. In addition to the G/T, it can remove thymine also from C/T and T/T mispairs in the order G/T >> C/T > T/T. It has no detectable activity on apyrimidinic sites and does not catalyze the removal of thymine from A/T pairs or from single-stranded DNA. It can also remove uracil and 5-bromouracil from mispairs with guanine.
Synonyms: hTDG
Tractability: Small molecule: a structure with a bound ligand is known. Antibody: its Gene Ontology location is reachable by antibodies, with high confidence. PROTAC: UniProt records ubiquitination sites on it; ubiquitination databases record sites on it; its protein half-life has been measured.
Target class: Enzyme; Hydrolase
Gene: Protein-coding gene on chromosome 12 (103,965,822 to 103,988,874, forward strand). Ensembl gene ENSG00000139372.
Subcellular location: Nucleus
Subcellular location (Human Protein Atlas): Nucleoplasm; Plasma membrane
Pathways (Reactome):
DNA Repair: Cleavage of the damaged pyrimidine; Displacement of DNA glycosylase by APEX1; Recognition and association of DNA glycosylase with site containing an affected pyrimidine
Gene expression (Transcription): TET1,2,3 and TDG demethylate DNA
Metabolism of proteins: SUMOylation of DNA damage response and repair proteins
Gene Ontology:
Molecular function: ATP binding; chloride ion binding; DNA N-glycosylase activity; double-stranded DNA binding; G/U mismatch-specific uracil-DNA glycosylase activity; magnesium ion binding; mismatched DNA binding; nucleic acid binding; protein binding; pyrimidine-specific mismatch base pair DNA N-glycosylase activity; sodium ion binding; SUMO binding; uracil DNA N-glycosylase activity; damaged DNA binding; DNA binding; G/T mismatch-specific thymine-DNA glycosylase activity; mismatch base pair DNA N-glycosylase activity; protein kinase C binding; transcription coregulator activity
Biological process: base-excision repair; base-excision repair, AP site formation; chromosomal 5-methylcytosine DNA demethylation, oxidation pathway; depyrimidination; epigenetic regulation of gene expression; regulation of embryonic development
Cellular component: nucleoplasm; nucleus; PML body
Genetic constraint (gnomAD): Loss-of-function variants: 25 observed, 43.07 expected, observed/expected ratio (o/e) 0.58, 90% interval 0.42 to 0.81. The upper end of that interval is the gene's LOEUF score, 0.81, which puts it in group 3 of 6, group 1 being the genes least tolerant of losing a copy. Missense variants: 304 observed, 448.81 expected, observed/expected ratio (o/e) 0.68, 90% interval 0.62 to 0.75. Synonymous variants: 115 observed, 144.07 expected, observed/expected ratio (o/e) 0.8, 90% interval 0.69 to 0.93.
Homologues: Orthologues: chimpanzee TDG (99% identical), macaque TDG (98% identical), pig TDG (91% identical), dog TDG (90% identical), mouse Tdg (88% identical), rat Tdg (86% identical), guinea pig TDG (81% identical), rabbit TDG (80% identical), tropical clawed frog tdg (63% identical), zebrafish tdg.1 (54% identical), zebrafish tdg.2 (49% identical), Drosophila melanogaster Tdg (33% identical).
Diseases named in the same sentence as TDG in open-access papers:
TDG is named in the same sentence as 53 diseases in open-access papers, as found by Europe PMC text mining. Sharing a sentence is not in itself a finding about the gene and the disease. The quoted sentences say what the papers report.
breast carcinoma (15 papers, 2014 to 2025). "In 2015, Shao and colleagues also confirmed that reduced expression of TET family genes, as well as TDG, are associated with poor prognosis of patients with early breast cancer." (PMID 34885145, 2021). "Expression of mRNAs encoding TET1–3 and TDG in 162 breast cancer tissues was quantified using real-time polymerase chain reaction analysis." (PMID 26207381, 2015). "In this present study, we further analyzed the association between the expression of mRNAs encoding TET1–3 and TDG with the prognosis of breast cancer patients." (PMID 26207381, 2015). "The authors proposed that the unexpected 5caC increase in some breast cancers may be due to thymine DNA glycosylase (TDG) loss-of-function." (PMID 34885145, 2021). "Mechanistically, polyamines derived from arginine metabolism promote DNA hypomethylation via thymine DNA glycosylase (TDG), enhancing the immunosuppressive function of TAMs and facilitating malignant progression in breast cancer." (PMID 41459510, 2025). "The intricate relationship between KYNA and TDG serves as a complex and dynamic regulator of estrogen signaling, with potential implications for understanding and treating diseases such as breast cancer, metabolic disorders, and neurodegeneration." (PMID 38969725, 2024). "In order to determine the prognostic role of TET family proteins and DNA glycosylase (TDG) in patients with early breast cancer, the expression of mRNAs encoding TET1-3 and TDG in 162 breast cancer tissues was quantified." (PMID 32375881, 2020). "Utilizing a combination of functional genomic analysis and biological assays, we have identified a role for TDG in E2-dependant signaling in MCF7 breast cancer cells." (PMID 29378668, 2018). "The purpose of this study was to determine the prognostic role of ten eleven translocation (TET) family proteins and DNA glycosylase (TDG) in patients with early breast cancer (EBC)." (PMID 26207381, 2015). "Based on our results that TDG expression in breast cancer patients corresponds with its level in controls we hypothesize TDG might not affect the level of 5-fC and 5-caC at gene’s level." (PMID 38499584, 2024). "Collectively our findings suggest that TDG plays a central role in mediating the transcriptional and functional effects of E2 in breast cancer and may prove to be an effective therapeutic target." (PMID 29378668, 2018). "Seven genes were shared between prostate and positive breast cancer responders (TRNT1, NUFIP1, TDG, HSPA8, OTUD6B, RBM12, and DENND3)." (PMID 35520391, 2022). "Using ChIP-Seq we generate a global profile of thymine DNA glycosylase (TDG), an ER coactivator that plays an essential role in DNA demethylation, in response to E2 in the MCF7 breast cancer cell line." (PMID 29378668, 2018). "Taken together, our findings suggest that TDG’s role in Wnt signaling may perhaps extend outside of CRC and play an important role in breast cancer." (PMID 29378668, 2018). "The observation that TDG depletion in MCF7 breast cancer cells leads to no accumulation of 5fC/5caC supports reports that the glycosylase activity of TDG is dispensable for E2-mediated signaling and instead it is TDGs ability to act as a coactivator that potentiates ER activity." (PMID 29378668, 2018). "To investigate whether TDG plays a functional role in E2 signaling in breast cancer, we engineered an MCF7 TDG knockout cell line using CRISPR technology and found that TDG knockout and depletion leads to defects in E2-mediated proliferation and sensitizes MCF7 cells to the anti-estrogen, tamoxifen." (PMID 29378668, 2018). "However, Cox regression analysis did not indicate TET1, 2, 3 and TDG mRNAs were independent predictors of breast cancer." (PMID 26207381, 2015). "The proof whether other proteins as well as TDG may serve as prognostic markers of breast cancer is lacking." (PMID 26207381, 2015). "Breast cancer patients did not significantly differ from control group in terms of TET1, TET2, and TDG mRNA expression." (PMID 38499584, 2024).
colorectal cancer (11 papers, 2006 to 2025). A primary or metastatic malignant neoplasm that affects the colon or rectum. "SNPs in the vitamin D receptor gene have also been linked to decreased risk in prostate cancer in African American men and rs1866074 near the thymine DNA glycosylase gene were reported to be correlated with lower colorectal cancer risk." (PMID 32881892, 2020). "The relationship between TDG and cancer has been studied by a number of research groups who have suggested that genetic variants in TDG and other DNA repair genes confer susceptibility to colorectal cancer." (PMID 31239841, 2019). "Meanwhile, germline mutations in TDG were also detected in patients with familial colorectal cancer." (PMID 26544625, 2015). "Thymine DNA glycosylase (TDG) is highly expressed in colorectal cancer and interacts with the transcription factor TCF4." (PMID 40001953, 2025). "Rather than functioning as a tumor suppressor, TDG KO inhibited the growth of colorectal cancer when xenografted on nude mice, and TDG expression was upregulated in human colorectal cancer." (PMID 37762489, 2023). "Wnt signaling was a particularly interesting finding as TDG has recently been shown to directly upregulate components of Wnt signaling pathway in colorectal cancer (CRC), and TDG depletion inhibited proliferation of CRC cells both in vitro and in vivo." (PMID 29378668, 2018). "Interestingly, this increase occurred in female mice, consistent with TCGA data showing that among colorectal cancer (CRC) cases, the lowest quartile of TDG and APC expression is associated with an excess of female cases." (PMID 36618446, 2021). "There is a significant relationship between TDG gene function and colorectal cancer progression." (PMID 31239841, 2019). "Thus, there is a significant relationship between TDG gene function and colorectal cancer progression." (PMID 31239841, 2019). "More recent work found that TDG expression levels are upregulated in colorectal carcinoma (CRC) and that TDG serves to regulate Wnt signaling, a key driver for CRC." (PMID 25375110, 2014). "In the human colorectal cancer (CRC) TCGA database, the subset of patients with TDG and APC expression in the lowest quartile exhibits an excess of female cases." (PMID 29163805, 2017).
melanoma (9 papers, 2019 to 2024). A malignant, usually aggressive tumor composed of atypical, neoplastic melanocytes. "More recently, utilizing melanoma cell line models it was shown that inactivation of TDG causes cell cycle arrest and senescence along with increased DNA methylation at a subset of CpG sites." (PMID 35159032, 2022). "Here we show that TDG knockdown in melanoma cell lines causes cell cycle arrest, senescence, and death by mitotic alterations; alters the transcriptome and methylome; and impairs xenograft tumor formation." (PMID 30674989, 2019). "Gene expression profiling of TDG knockdown cells showed upregulation of known melanoma SASP genes, hallmark of senescence, and downregulation of cell cycle factors, such as E2F target genes and DNA replication genes, which may explain the cell cycle arrest." (PMID 30674989, 2019). "For instance, TDG is highly expressed in melanoma and, upon depletion, induces cell cycle arrest and senescence, thus inhibiting cell proliferation." (PMID 38914477, 2024). "Alterations in TDG expression are a biomarker for melanoma and colorectal cancers (CRCs) and play a role with TET1 in genomic instability through DNA demethylation and inflammation." (PMID 38914477, 2024). "Using a high throughput screening assay dependent on TDG catalytic activity, the authors identified first generation TDG inhibitors that decreased viability and clonogenic capacity of melanoma lines." (PMID 35159032, 2022). "Concomitantly, gene set enrichment analysis of TDG knockdown melanoma cells revealed the enrichment of E2F target genes, which are known to be involved in cell cycle progression and DNA replication and repair." (PMID 36618446, 2021). "The appearance of dendritic processes in melanoma cells upon TDG knockdown is a distinctive morphological feature that renders them similar to dendritic melanocytes, which are found in BrafV600E-induced nevi and stain positive for SA-β-Gal activity." (PMID 30674989, 2019). "Given the importance of DNA demethylation in melanomagenesis and TDG requirement for neural crest development, we began exploring the role of TDG in melanoma." (PMID 30674989, 2019). "Our studies show that TDG is required for melanoma cell proliferation, survival, and tumor formation." (PMID 30674989, 2019). "We have recently identified TDG as an anticancer target in melanoma." (PMID 36618446, 2021). "Thymine–DNA glycosylase (TDG) has recently been validated as a possible drug target in melanoma: its knockdown causes cell cycle arrest, senescence, and cell death in melanoma cell lines but not in normal cells and prevents tumor growth in a xenograft model." (PMID 32354123, 2020). "The antiproliferative effects of TDG knockdown in cancer cells raise the possibility that small molecule inhibitors that catalytically inactivate TDG may be useful for melanoma treatment." (PMID 30674989, 2019). "Given the role of TDG in DNA demethylation, we began to investigate whether TDG knockdown alters the epigenome of melanoma cell lines." (PMID 30674989, 2019). "Candidate TDG inhibitors, identified through a high-throughput fluorescence-based screen, reduced viability and clonogenic capacity of melanoma cell lines and increased cellular levels of 5-carboxylcytosine, the last intermediate in DNA demethylation, indicating successful on-target activity." (PMID 30674989, 2019). "Thus TDG knockdown SK28 melanoma cells undergo senescence by repression of cell cycle progression genes and expression of SASP genes." (PMID 30674989, 2019). "By potentially disrupting both DNA repair and the epigenetic state, targeting TDG may represent a completely new approach to melanoma therapy." (PMID 30674989, 2019). "In this study, through cell culture and mouse xenograft studies, we establish the importance of TDG in maintaining the viability of melanoma cells, and using a DNA repair molecular beacon assay, we isolate first-generation TDG inhibitors and characterize their anticancer activity." (PMID 30674989, 2019).
melanoma (continued). "Notably, TDG has previously been proposed as a therapeutic target to treat melanoma." (PMID 39137780, 2024). "Another group has reported that disruption of DNA repair and epigenetic state by knockdown of a BER enzyme thymine DNA glycosylase (TDG) may be a potent strategy against melanoma, and furthermore, the group also evaluated candidate inhibitors of TDG for the treatment of melanoma." (PMID 33800547, 2021). "These compounds also led to a dose-dependent reduction in cell viability of melanoma cells with IC50 values close to 10 μM, which suggests that interfering with the DNA repair and epigenetic activity of TDG may represent a new and valid approach for the treatment of melanoma." (PMID 33287345, 2020). "Thus it is possible that TDG knockdown causes senescence in melanoma cells by decreasing the levels and activity of p300 and MITF, which in turn may further deplete TDG by reducing its transcription." (PMID 30674989, 2019). "Thus dendrites may be a morphological feature of TDG knockdown-induced senescence of melanoma cells." (PMID 30674989, 2019). "Knockdown of TDG also led to altered metabolic status with reduced expression of genes involved in oxidative phosphorylation; the critical role of oxidative phosphorylation in promoting melanoma growth has been recently highlighted by elucidation of the role of SAMMSON." (PMID 30674989, 2019). "Thus TDG knockdown reduces the ability of melanoma cells to form tumors in xenotransplant assay." (PMID 30674989, 2019). "We used the C8 lentivirus expressing an short hairpin RNA (shRNA) against TDG to knock down the TDG expression in Mel501, Mull, and SK28 melanoma lines." (PMID 30674989, 2019).
multiple myeloma (5 papers, 2015 to 2022). "Aberrant DNA methylation of the TDG (thymine DNA glycosylase) gene is reported in multiple myeloma cells and is related to genomic instability in multiple myeloma." (PMID 26967246, 2016). "It has been reported that TDG expression can be inhibited in multiple myeloma cell lines through promoter methylation, and indeed there is a CpG island around the first exon of mouse TDG gene." (PMID 26544625, 2015).
pancreatic cancer (4 papers, 2015 to 2026). "Oncogenic Ras mutations occur in more than 90% of pancreatic cancer of all grades, so we next examined the expression of TDG in human pancreatic cancer." (PMID 26544625, 2015). "As expected, TDG were down-regulated in K-Ras mutated pancreatic cancer cell lines Miapaca-2 and Panc-1, compared with the Bxpc-3 in which the K-Ras gene was wild type." (PMID 26544625, 2015). "For example, human TDG actually locates at chromosome 12q22-q24.1, one of regions frequently lost in many human cancers including gastric cancer and pancreatic cancer." (PMID 26544625, 2015). "Furthermore, oncogenic Ras regulates the ING4–thymine-DNA glycosylase (TDG)–Fas axis to trigger apoptosis in pancreatic cancer cell lines." (PMID 30643005, 2019). "TDG suppressed in vivo tumorigenicity of xenograft pancreatic cancer." (PMID 26544625, 2015). "Next, we explored the role of TDG as a tumor suppressor in pancreatic cancer." (PMID 26544625, 2015). "Importantly, TDG expression in human pancreatic cancer tissues were significantly decreased when compared with its expression in normal pancreas or pancreas with chronic inflammation or benign tumors." (PMID 26544625, 2015). "However, the in vivo growth of tumors formed by pancreatic cancer cells with ectopic TDG expression was significantly retarded." (PMID 26544625, 2015). "Therefore, reversing Ras-mediated downregulation of TDG expression and subsequent Fas expression could a promising approach for the target therapy of pancreatic cancer and other Ras-driven cancers." (PMID 26544625, 2015). "Consequently, TDG effectively suppressed in vivo tumorigenecity of xenograft pancreatic cancer." (PMID 26544625, 2015). "Therefore, reversing Ras-mediated ING4 suppression to activate TDG expression and subsequent Fas expression could a promising approach for the target therapy of pancreatic cancer and other Ras-driven cancers." (PMID 26544625, 2015). "Consistently, FasL induced apoptosis of pancreatic cancer cells only in the presence but not absence of TDG expression." (PMID 26544625, 2015).
rectal cancer (3 papers, 2016 to 2022). A primary or metastatic malignant neoplasm that affects the rectum. "TDG inactivation may contribute to the aggressive phenotype of rectal cancer." (PMID 35414793, 2022).
glioblastoma (2 papers, 2021 to 2024). The most malignant astrocytic tumor (WHO grade IV). "It was also observed that TDG was most expressed in glioblastomas compared to other histological subtypes." (PMID 39090080, 2024).